NPM1 (nucleophosmin 1)
Diseases named in the same sentence as NPM1 in open-access papers (continued):
Sharing a sentence is not in itself a finding about the gene and the disease.
acute myeloid leukemia (continued). "Here, the authors show that NPM1, a gene frequently mutated in acute myeloid leukaemia, protects polη from proteasomal degradation, and that NPM1 deficiency causes a TLS defect." (PMID 25421715, 2014). "Mutations of NPM1 were also described in hematological malignancies, and it has been suggested that NPM1-mutated acute myeloid leukemia is a distinct leukemia entity." (PMID 24410879, 2014). "NPM1 mutations can be found in 35% of patients with cytogenetically normal acute myeloid leukemia (AML)." (PMID 25299584, 2014). "In leukemia, however, so far only one study associated a SNP in the 3′UTR of the NPM1 gene with adverse outcome in acute myeloid leukemia." (PMID 24886876, 2014). "NPM1 mutations are frequent in acute myeloid leukemia (AML) and are characterized by aberrant NPM1 accumulation in the cytoplasm." (PMID 23874639, 2013). "Nucleophosmin mutations (NPM1m) occur in about one-third of acute myeloid leukaemias (AMLs), and the current classification of myeloid neoplasms defined a recent entity of NPM1-mutated AML with distinct biological, clinical, and prognostic features." (PMID 23691328, 2013). "We previously found NPM1 exon 12 somatic mutations in approximately 60% of adult acute myeloid leukemia (AML) and normal karyotype." (PMID 20877721, 2010). "Another previous study demonstrated the cytoplasmic location of NPM and the mutation of exon 12 of the NPM1 gene as a hallmark of a large subgroup of primary acute myelogenous leukaemia (NPMc+ AML)." (PMID 17245342, 2007). "NPM1 variants have an important role in embryonic development and mutations of the genes encoding these proteins have been shown to be involved in acute myeloid leukemia." (PMID 16646973, 2006). "Furthermore, PAMT-001 demonstrated potential for use in precision medicine, particularly for patients with chemotherapy-resistant and NPM1-mutated acute myeloid leukemia." (PMID 41881965, 2026). "Altered expression of Let-7 miRNAs has been associated with mutated form of NPM1 in acute myeloid leukemia, suggesting that NPM1 may influence miRNA expression in CRC." (PMID 40438109, 2025). "Such an approach could, in principle, advance analytical technology for the detection of NPM1 mutations in leukemic blasts, thus offering a promising tool for biological studies and diagnosis of NPM1-related acute myeloid leukemia (AML)." (PMID 40603297, 2025). "APL-like acute myeloid leukemia with NPM1, IDH2, and SETD2 mutations was made." (PMID 39432585, 2024). "NPM1 gene mutations play an important role in acute myeloid leukemia." (PMID 38671491, 2024). "Somatic NPM1 variants are instead associated with acute myeloid leukaemia (OMIM #601,626)." (PMID 38778413, 2024). "Acute myeloid leukemia (AML) with nucleophosmin (NPM1) mutation was fully accepted as a specific AML category in the 2017 World Health Organization (WHO) classification of hematologic neoplasms, with the requirement of a blast cell count ≥ 20% for its diagnosis." (PMID 38398096, 2024). "Moreover, decreased expression of H1.3 is associated with a bad prognosis in acute myeloid leukemia patients with mutations in NPM1, while mutations in several RD subtypes are recurrent in B-cell lymphomas." (PMID 39456154, 2024). "A 70-year-old man was diagnosed with acute myeloid leukemia with NPM1, IDH2, and SETD2 mutations." (PMID 39432585, 2024). "Although NPM1 should shuttle between the nucleus and cytoplasm, its predominant presence in the cytoplasm indicates abnormalities or severe mutations, including cancer (acute myeloid leukemia, AML) and viral infection." (PMID 39120297, 2024). "NPM1 mutations happen in approximately one-third of acute myeloid leukemias (AMLs)." (PMID 36313673, 2022). "The experimental studies targeted nucleophosmin-1 (NPM1)-mutated acute myeloid leukaemia, multiple myeloma, certain lymphomas, lung cancers, several autoimmune diseases, graft versus host disease, certain neurological diseases, and idiopathic pulmonary fibrosis." (PMID 36518307, 2022).
acute myeloid leukemia (continued). "The patient was eventually diagnosed with acute myeloid leukaemia (AML) with mutated NPM1." (PMID 35844705, 2021). "The C-terminal aminoacidic sequence from NPM1-mutated protein, absent in normal human tissues, may serve as a leukemia-specific antigen and can be considered an ideal target for NPM1-mutated acute myeloid leukemia (AML) immunotherapy." (PMID 34502069, 2021). "Moreover, the frameshift mutations in nucleophosmin 1 (NPM1), a genetic event in about one-third of patients with acute myeloid leukemia (AML), lead to increased Akt activation that renders hypersensitivity to Akt inhibitors." (PMID 34419139, 2021). "One-third of adult acute myeloid leukemia (AML) harbors NPM1 mutations." (PMID 33525388, 2021). "All these genetic alterations usually perturb the normal cellular traffic of NPM1 protein in malignant cells, but we will focus here on the biological and clinical significance of NPM1 gene mutations occurring in acute myeloid leukemia (AML) and other myeloid neoplasms." (PMID 33255988, 2020). "NPM1 gene mutation is a founding event in acute myeloid leukaemia." (PMID 31048683, 2019). "We demonstrate single-cell genotyping of the NPM1 type A mutation, an important prognostic indicator in acute myeloid leukemia, on single cells of the cell line OCI-AML3, describing a more complex zygosity distribution than would be predicted via bulk analysis." (PMID 29718986, 2018). "The objective was to evaluate the prognostic impact of pre-transplant minimal residual disease (MRD) as determined by real-time quantitative polymerase chain reaction in 67 adult NPM1-mutated acute myeloid leukemia patients receiving allogeneic hematopoietic stem cell transplantation (HSCT)." (PMID 27471865, 2016). "Nucleophosmin 1 (NPM1) mutations are the most common single gene abnormality detected in adult acute myeloid leukemia (AML) and might represent the initiating event for AML development in about 60% of AML patients without causative cytogenetic abnormalities." (PMID 25992555, 2015). "In this light, the frequent co-occurrence of DNMT3A and NPM1 mutations suggests that the former behave as “rafts” that enable NPM1 mutant clones to be founded and expanded, thus facilitating onward evolution toward acute myeloid leukemia." (PMID 25732814, 2015). "DNMT3A, FLT3, and NPM1 mutations are among the most common genomic alterations in de novo acute myeloid leukemia (AML) and play a key role in the pathogenesis and evolution of the disease, particularly in the absence of AML-associated recurrent cytogenetic abnormalities." (PMID 25281355, 2014). "Somatic Nucleophosmin (NPM1) mutation frequently occurs in acute myeloid leukemia (AML), but its role in leukemogenesis remains unclear." (PMID 23226219, 2012). "Acute myeloid leukaemia (AML) with nucleophosmin-1 (NPM1) mutation is a major subtype of AML." (PMID 22348345, 2012). "NPM1-mutated (NPM1-mut) acute myeloid leukemia (AML) is generally associated with a more favorable outcome, although the presence of additional gene mutations can influence patient prognosis." (PMID 41535568, 2026). "NPM1 represents the most frequently mutated gene in acute myeloid leukemia (AML), accounting for 30% of AML cases, and traditionally confers a better prognosis, although this depends on the pattern of co-mutated genes in the specific patient." (PMID 39941372, 2025). "Acute myeloid leukemia (AML) with nucleophosmin 1 (NPM1) mutation represents a distinctive subpopulation with unique molecular and clinical features." (PMID 41374935, 2025). "NPM1 is frequently mutated and rearranged in tumors, particularly in acute myeloid leukemia (AML), where it is altered in about one‐third of patients." (PMID 40705480, 2025).
acute myeloid leukemia (continued). "Moreover, in 50% of acute myeloid leukemias, NPM1 is mutated and exhibits cytoplasmic localization." (PMID 40133262, 2025). "Acute myeloid leukemia (AML), for example, has over 20 known molecular subtypes, arising from specific genetic alterations such as NPM1 mutations, FLT3-ITD, CEBPA mutations, and various chromosomal rearrangements." (PMID 40940796, 2025). "Dysregulation of the menin-KMT2A and polycomb repressive (PRC1/2) complexes in MLL-rearranged and NPM1-mutated acute myeloid leukemia (AML) contributes to the aberrant expression of self-renewal genes in hematopoietic stem and progenitor cells." (PMID 39607901, 2025). "Background/Objectives: This study investigates genomic alterations (GA) between NPM1-mutated (NPM1mut) and wild-type (NPM1wt) acute myeloid leukemia (AML), aiming to better understand the AML genomic profile." (PMID 40867339, 2025). "Molecular failure in NPM1-mutated acute myeloid leukemia (AML) inevitably progresses to frank relapse if untreated." (PMID 38039513, 2024). "NPM1 mutation is more frequently observed in adult acute myeloid leukemia (AML) with a normal karyotype, occurring in 20%–30% of AML patients." (PMID 39126219, 2024). "Nucleophosmin 1 (NPM1) mutations occur in approximately one‐third cases of adult de novo acute myeloid leukemia (AML)." (PMID 38633114, 2024). "Initially, we extensively describe the rarest case, a patient diagnosed with chronic eosinophilic leukemia (CEL) with less than 1% bone marrow blasts associated with an NPM1 mutation who progressed to an acute myeloid leukemia (AML)." (PMID 38398096, 2024). "Patients with Core-Binding Factor (CBF) and NPM1-mutated acute myeloid leukemia (AML) can be monitored by quantitative PCR after having achieved first complete remission (CR) to detect morphologic relapse and drive preemptive therapy." (PMID 39020060, 2024). "The nucleophosmin 1 (NPM1) gene is mutated in approximately one-third of newly diagnosed acute myeloid leukemia (AML) cases." (PMID 36831522, 2023). "To date, the critical role of NPM1 mutations in the pathogenesis and clinical course of acute myeloid leukemia (AML) has been described." (PMID 36282861, 2022). "Acute myeloid leukemia (AML) with nucleophosmin 1 (NPM1) mutations exhibits distinct biological and clinical features, accounting for approximately one-third of AML." (PMID 35211409, 2022). "NPM1-mutated acute myeloid leukemia (AML) represents about one-third of all adult AML and, due its unique clinicopathological and genetic features, is recognized as a leukemia entity of the World Health Organization (WHO) Classification of myeloid neoplasms." (PMID 35568767, 2022). "Blasts with cup‐like morphology are well recognized in acute myeloid leukemia (AML), being frequently associated with a normal karyotype and mutated NPM1 and/or FLT3‐ITD." (PMID 36051070, 2022). "Current guidelines recommend that Acute Myeloid Leukemia (AML) patients with NPM1 mutations should be monitored for measurable residual disease by quantifying the transcripts and normalizing them to ABL1 transcripts." (PMID 36467801, 2022). "In Acute Myeloid Leukemia (AML), NPM1 is frequently mutated, and exhibits an aberrant cytoplasmic localization (NPM1c)." (PMID 35408798, 2022). "The mutation of NPM1 plays a unique role in the pathogenesis of acute myeloid leukemia (AML) and is seen in about 35% of AML patients, which makes NPM1-mutated AML the single largest unique group of AML." (PMID 35054502, 2022). "Mutations of NPM1 gene are the most frequent genetic lesion in acute myeloid leukemia (AML), being detectable in about one-third of adult AML and 50–60% of AML with normal karyotype." (PMID 36008542, 2022). "In 30% of patients with acute myeloid leukemia (AML), NPM1 mutations typically consist of 4-base pair frameshift duplication or insertion within exon 12 of the gene." (PMID 35621629, 2022).
acute myeloid leukemia (continued). "The majority of patients with acute myeloid leukemia (AML) with the NPM1 mutation achieve remission with intensive chemotherapy." (PMID 36619478, 2022). "NPM1 mutations are the most common genetic alteration in acute myeloid leukemia (AML), detected in about 30–35% of adult AML and more than 50% of AML with normal karyotype." (PMID 36008542, 2022). "NPM1-mutated (NPM1mut) acute myeloid leukemia (AML) comprises about 30% of newly diagnosed AML in adults." (PMID 33525388, 2021). "The World Health Organization (WHO) classification has defined acute myeloid leukemia (AML) with NPM1 mutations as a distinct entity." (PMID 34899858, 2021). "Those workers showed that Nucleophosmin (NPM1), a gene commonly mutated in acute myeloid leukemia (AML), interacts with the Pol η catalytic core and promotes excessive degradation of the polymerase." (PMID 34663880, 2021). "The purpose of this study was to analyze the association between next-generation sequencing (NGS) genotypic profiles and conventional clinicopathologic characteristics in patients with acute myeloid leukemia (AML) with NPM1 mutation (NPM1mut)." (PMID 34238278, 2021). "NPM1 mutations have been identified in about one-third of adults and 6–8% of pediatric patients with acute myeloid leukemia (AML), accounting for a distinct entity." (PMID 34298672, 2021). "In patients with Acute Myeloid Leukemia (AML) the most frequent acquired molecular abnormalities and important prognostic indicators is nucleophosmin-1 (NPM1) mutations." (PMID 34795724, 2021). "As antigen domain, we either fused a cytomegalovirus (CMV)-specific epitope or a neoantigen derived from mutated NPM1 (mNPM1), which occurs in 30–35% of acute myeloid leukemia (AML)." (PMID 33281829, 2020). "Differential expression of LAPTM4B and MIR155HG was confirmed in a small cohort of young adult NPM1-mutated cytogenetically normal acute myeloid leukemia (CN-AML) patients." (PMID 30753220, 2019). "Mutations in NPM1 are a major cause of acute myeloid leukemia (AML) being present in 20–30% of the cases." (PMID 30781559, 2019). "Acute myeloid leukemia (AML) with mutated nucleophosmin (NPM1) is acknowledged as a distinct leukemia entity in the 2016 updated World Health Organization (WHO) classification." (PMID 31777586, 2019). "We present a case report of a patient with acute myeloid leukemia (AML) characterized by the simultaneous presence of nucleophosmin 1 (NPM1) mutation and the breakpoint cluster region-Abelson (BCR-ABL) fusion oncogene." (PMID 31110828, 2019). "Acute myeloid leukemia (AML) with mutated nucleophosmin (NPM1) has been recognized as a distinct leukemia entity in the 2016 World Health Organization (WHO) classification." (PMID 29343273, 2018). "The Npm1 mutation, which is the most frequent genetic alteration in acute myeloid leukemia (AML), can be characterized in this knock-in permissive model." (PMID 30079312, 2018). "Nucleophosmin-1 (NPM1) mutations have prognostic importance in acute myeloid leukemia (AML) patients with intermediate-risk karyotype at diagnosis." (PMID 29129825, 2018). "Acute myeloid leukemia (AML) with NPM1 gene mutations is currently recognized as a distinct entity, due to its unique biological and clinical features." (PMID 30404199, 2018). "Furthermore NPM1 is the most frequently mutated protein in acute myeloid leukemia (AML) patients." (PMID 28920929, 2017). "Mutations of the gene for nucleophosmin (NPM1) are the most frequent genetic aberration in patients with acute myeloid leukemia (AML)." (PMID 28384310, 2017). "Mutations of the nucleophosmin-1 (NPM1) gene in cytogenetically normal (CN) acute myeloid leukemia (AML) identify a group of patients with more favorable prognosis." (PMID 29221119, 2017).
acute myeloid leukemia (continued). "NPM1 has been identified as the most frequently mutated gene in acute myeloid leukemia (AML) patients, in particular specific mutations in the exon 12 of the NPM1 gene occur, accounting for approximately 30% of AML cases." (PMID 27494862, 2016). "Here, we present a rare case of a 34-year-old patient who was initially diagnosed with acute myeloid leukemia (AML) with mutated NPM1." (PMID 27752371, 2016). "Mutations in the nucleophosmin 1 (NPM1) gene are the most frequent genetic alteration in acute myeloid leukemia (AML)." (PMID 27669739, 2016). "Acute myeloid leukemia (AML) carrying nucleophosmin 1 (NPM1) mutations (NPMc+) is regarded as a separate entity of myeloid neoplasms due to its distinct biological and clinical features." (PMID 27525194, 2015). "Nucleophosmin 1 (NPM1) mutations are frequently found in patients with acute myeloid leukemia (AML) and the newly generated sequences were suggested to induce immune response contributing to the relatively favorable outcome of patients in this AML subset." (PMID 25992555, 2015). "NPM1 mutations represent frequent genetic alterations in patients with acute myeloid leukemia (AML) associated with a favorable prognosis." (PMID 25299584, 2014). "Nucleophosmin (NPM1) gene mutations are among the most common gene alteration in acute myeloid leukemia (AML) and mainly occur in AML with normal karyotype (NK-AML) (11, –13)." (PMID 24032106, 2013). "In contrast, miR-196b was over-expressed in patients with acute myeloid leukemia (AML) and the carcinogenic NPM1 mutation." (PMID 23894305, 2013). "Altered NPM1 expression was observed in many types of tumors, and mutated NPM1 is frequently detected in human hematopoietic malignancies, especially in acute myeloid leukemia (AML)." (PMID 22631075, 2012). "As far as NPM1 is concerned, mutations in this gene drive tumorigenesis in acute myeloid leukemia (AML), but its role in solid tumors has been controversial." (PMID 23113900, 2012). "Mlf1 (myeloid leukemia factor 1) is associated with myeloid leukemia; Mlf1 is fused to nucleophosmin (Npm1) in 1% of acute myeloid leukemia (AML) cases and is overexpressed in 25% of cases of AML associated with myelodysplastic syndrome." (PMID 23300604, 2012). "Mutations in the nucleophosmin 1 gene (NPM1) are common and recurrent molecular abnormalities in acute myeloid leukemia (AML)." (PMID 40557158, 2025). "Finally, we show that the use of PDCD4-derived peptides to block the interaction between NPMc+ and PDCD4 exhibits a promising therapeutic effect in NPM1-mutated acute myeloid leukemia (AML) mice." (PMID 41234771, 2025). "The bone-marrow niche serves as a critical microenvironment that supports the survival, proliferation, and drug resistance of acute myeloid leukemia (AML) blasts, particularly in subsets with specific genetic aberrations such as NPM1 mutation." (PMID 41347170, 2025). "This compound demonstrated strong efficacy in preclinical models of acute myeloid leukemia (AML) carrying MLL rearrangements and NPM1 mutations." (PMID 39327672, 2025). "Targeted next-generation sequencing identified a mutation in NPM1 and according to the WHO 5th edition criteria, the patient was diagnosed with acute myeloid leukemia (AML) with NPM1 mutation." (PMID 40567444, 2025). "We found that ATG4B exhibited significantly high expression levels in various acute myeloid leukemia (AML) with diverse molecular subgroups (e.g., MLL‐rearrangement, FLT3‐ITD mutation, and NPM1 mutation, etc.)." (PMID 40788108, 2025). "In acute myeloid leukemia with MLL1 rearrangement (MLL1r) or mutant NPM1 (mtNPM1), treatment with menin inhibitors (MIs) can induce clinical remission; however, many patients either exhibit resistance or experience relapse, with some acquiring menin mutations." (PMID 40003685, 2025).